TNP2 (transition protein 2)
Description:
Plays a key role in the replacement of histones to protamine in the elongating spermatids of mammals. In condensing spermatids, loaded onto the nucleosomes, where it promotes the recruitment and processing of protamines, which are responsible for histone eviction.
Synonyms: TP2
Tractability: No criterion of Open Targets' tractability assessment is met for any kind of drug.
Gene: Protein-coding gene on chromosome 16 (11,267,748 to 11,269,533, reverse strand). Ensembl gene ENSG00000178279.
Subcellular location: Nucleus; Nucleus, nucleolus; Chromosome
Gene Ontology:
Molecular function: protein binding; zinc ion binding; DNA binding
Biological process: acrosome reaction; penetration of zona pellucida; positive regulation of protein processing; sperm DNA condensation; spermatogenesis
Cellular component: chromosome; nucleosome; nucleus; nucleolus
Genetic constraint (gnomAD): Loss-of-function variants: 10 observed, 9.57 expected, observed/expected ratio (o/e) 1.04, 90% interval 0.64 to 1.71. That is too few expected variants to judge how well the gene tolerates losing a copy. Missense variants: 215 observed, 183.86 expected, observed/expected ratio (o/e) 1.17, 90% interval 1.04 to 1.31. Synonymous variants: 78 observed, 63.83 expected, observed/expected ratio (o/e) 1.22, 90% interval 1.02 to 1.48.
Homologues: Orthologues: chimpanzee TNP2 (94% identical), macaque TNP2 (88% identical), dog TNP2 (56% identical), pig TNP2 (56% identical), mouse Tnp2 (36% identical), rat Tnp2 (36% identical).
Diseases named in the same sentence as TNP2 in open-access papers:
TNP2 is named in the same sentence as 13 diseases in open-access papers, as found by Europe PMC text mining. Sharing a sentence is not in itself a finding about the gene and the disease. The quoted sentences say what the papers report.
Infertility (7 papers, 2012 to 2025). "Next researches using linkage studies of SNPs in pedigrees and a larger population of infertile men should confirm the causal link between TNP2 gene polymorphisms and male infertility." (PMID 31583373, 2019). "So in this study, we decided to analyze the TNP2 gene mutations in Iranian infertile varicocele patients." (PMID 31583373, 2019). "PCR-SSCP and DNA sequencing were used to search for mutations in exons 1 & 2 of the TNP2 gene in 156 infertile patients with varicocele and 150 fertile men." (PMID 31583373, 2019). "Premature translation of Tnp2 mRNA in round spermatids by expressing a transgene with the 3′UTR of human growth hormone produced infertile male mice." (PMID 31541158, 2019). "However, Hist1h1a/Mcsp, Hist1h1t/Mcsp, Tnp2/Mcsp and Acr/Mcsp dKO male mice exhibited subfertility or near infertility." (PMID 38395975, 2024). "STRING and Cytoscape analyses presented seven genes, i.e., DDX5, TNP2, DDX3Y, TDRD6, SOHL2, DDX31, and SYCP3, as the hub genes involved in infertility with VASA co-function and protein–protein interaction." (PMID 36241908, 2022). "The ratio of infertility genes expression: DDX5, TNP2, DDX3Y, TDRD6, SOHL2, DDX31, and SYCP3 in infertility cell (azoospermia) in comparison to a normal cell." (PMID 36241908, 2022). "In the present study, to examine TNP2 gene alterations in relation to human male infertility, we assessed the prevalence of TNP gene SNPs in infertile patients." (PMID 31583373, 2019). "These proteins with high intrinsic disorder and LLPS propensity, such as myristoylated alanine rich C-kinase substrate (MARCKS; UniProt ID: P29966) and nuclear transition protein 2 (TNP2; UniProt ID: Q05952) could serve as potential targets for understanding acrosome deformities and infertility." (PMID 40407495, 2025). "The impaired function of oxidative phosphorylation could be the predominant reason for crossbred bull infertility; and significant downregulation of ZNF706, CRISP2, TNP2, and TNP1 genes indicates that they could serve as potential biomarkers for fertility in crossbred bulls." (PMID 34041237, 2021). "The lack of TNP1 and TNP2 leads to defects in sperm head, reduced sperm motility, and infertility." (PMID 34041237, 2021).
male infertility (6 papers, 2012 to 2024). The inability of the male to effect fertilization of an ovum after a specified period of unprotected intercourse. "Although a distinct pathway has not been found yet, the reduced transcription of postmeiotic genes, including Tnp1, Tnp2, Prm1 and Prm2, in Brwd1-defective testes has been suggested to cause male infertility." (PMID 34473250, 2021). "This study has evaluated frequency of six previously reported variations in protamine genes cluster consisted of reported mutations in PRM1, PRM2 and TNP2 and their relationship to male infertility in Iranian population." (PMID 25246894, 2012). "Defects in TNP2 proteins lead to abnormalities in sperm head due to acrosomal defects, impairing migration of the spermatozoa through the female genital tract and inability of the spermatozoa to penetrate the zonapellucida that cause male infertility." (PMID 25246894, 2012). "Some investigations presented a significant relationship between reduced protamine and transition protein 2 gene expressions and male infertility." (PMID 25246894, 2012). "Recent investigations represented different variations in PRM1, PRM2 and TNP2 gene sequences in human with various relationships to male infertility." (PMID 25246894, 2012). "This section will briefly highlight the role of the eight (TNP1, TNP2, PDHA2, LDHC, SPINK2, ODF1, ODF2, and PCDHB3) common DEGs in male infertility as obtained from our findings." (PMID 35207567, 2022).
asthenozoospermia (2 papers, 2017 to 2020). "Nuclear transition protein 2 (TNP2) transcript is associated with sub-optimal semen quality, teratozoospermia and asthenozoospermia." (PMID 33069132, 2020).
teratozoospermia (2 papers, 2020 to 2025). "Notably, while diminished TNP2 expression is associated with impaired sperm quality, elevated TNP2 expression has been linked to abnormal sperm morphology and teratozoospermia." (PMID 40938846, 2025).
breast carcinoma (1 paper, 2018). "TNP-1, but not TNP-2, induced apparent autophagy in the cells derived from the breast cancer patient." (PMID 30315154, 2018).
Leydig cell tumor (1 paper, 2014). A sex cord-stromal tumor occurring in the testis and rarely in the ovary. "The luciferase assay also indicated that bta-miR-154 directly targets TNP2 in a murine Leydig cell tumor cell line." (PMID 24416221, 2014).
Sertoli Cell-Only Syndrome (1 paper, 2025). A type of male infertility in which no germ cells are visible in any of the biopsied SEMINIFEROUS TUBULES (type I) or in which germ cells are present in a minority of tubules (type II). "In this work, we observed a notable decrease in TNP2 expression within the SA group, aligning with earlier studies that indicate reduced TNP2 levels in individuals diagnosed with NOA, including SA and Sertoli cell-only syndrome (SCOS)." (PMID 40938846, 2025).
varicocele (1 paper, 2019). A condition characterized by the dilated tortuous veins of the spermatic cord with a marked left-sided predominance. "Because of the crucial role of nuclear transition proteins (TPs) in sperm DNA condensation and integrity, this case-control study was designed to study TNP2 gene nucleotide variations in Iranian patients with varicocele." (PMID 31583373, 2019).
cancer (2 papers, 2018 to 2019). A tumor composed of atypical neoplastic, often pleomorphic cells that invade other tissues. "Similar to CQ, 3-MA further enhanced the anti-cancer efficacy for TNP-1- but not TNP-2-mediated PTT, as the tumor weight of the TNP-1 + NIR + 3-MA group decreased by 91% compared to the PBS + NIR group, while the corresponding number was only 67% for the TNP-2 + NIR + 3-MA group." (PMID 30315154, 2018).
tumor (1 paper, 2018). "On the other hand, no statistically-significant difference in this ratio was observed between the wild-type and knockout tumors for TNP-2 + NIR treatment (43.82% for wild-type tumor and 47.08% for Atg5 knockout tumor, p > 0.05, Student’s t-test)." (PMID 30315154, 2018).
TNP2 also shares sentences with these, for which no sentence is quoted: Azoospermia (3 papers); oligospermia (2); toxoplasmosis (1).